MIR503HG (MIR503 host gene)
Synonyms: MGC16121; H19X
Gene: Long non-coding RNA gene on chromosome X (134,543,118 to 134,549,644, reverse strand). Ensembl gene ENSG00000223749.
Gene Ontology:
Biological process: miRNA-mediated post-transcriptional gene silencing
Cellular component: RISC complex
Diseases named in the same sentence as MIR503HG in open-access papers:
MIR503HG is named in the same sentence as 13 diseases in open-access papers, as found by Europe PMC text mining. Sharing a sentence is not in itself a finding about the gene and the disease. The quoted sentences say what the papers report.
hepatocellular carcinoma (2 papers, 2022 to 2025). A malignant tumor that arises from hepatocytes. "Similarly, in hepatocellular carcinoma, MIR503HG suppresses metastasis through the regulation of HNRNPA2B1 ubiquitination." (PMID 40490947, 2025). "In addition, it has been reported that the Mir503HG is involved in tumor metastasis in hepatocellular carcinoma." (PMID 36211451, 2022).
choriocarcinoma (1 paper, 2016). An aggressive malignant tumor arising from trophoblastic cells. "Based on their expression profile and their effects on migration and invasion in a model of choriocarcinoma, our study suggests a potential role for MIR503HG and LINC00629 genes in tumorigenesis and human reproduction, considering the similarity among normal placenta and germinal tissues to tumors." (PMID 27023770, 2016).
diabetes (1 paper, 2024). "Altogether, these findings highlighted MIR503HG as an essential and exclusive PP cell fate specification regulator with promising therapeutic potential for patients with diabetes." (PMID 38243869, 2024).
large cell-lymphoma (1 paper, 2024). "Conversely, in anaplastic lymphoma kinase-negative anaplastic large cell-lymphoma (ALK-negative ALCL) and non-small cell lung cancer MIR503HG is upregulated and mediates tumor-promoting effects." (PMID 39676172, 2024).
lymphoma (1 paper, 2019). A malignant (clonal) proliferation of B- lymphocytes or T- lymphocytes which involves the lymph nodes, bone marrow and/or extranodal sites. "More importantly, MIR503HG is the host gene of miR-503 and MIR503HG could induce the miR-503 expression in lymphoma, while miR-503 has been well-documented for its regulatory role in cell invasion and migration." (PMID 31467616, 2019).
ovarian carcinoma (1 paper, 2022). A malignant neoplasm originating from the surface ovarian epithelium. "MIR503 host gene (MIR503HG) acts as an important tumor suppressor in many human cancers, but its role and regulatory mechanism in ovarian cancer need to be further studied." (PMID 35771155, 2022). "In conclusion, MIR503HG expression was downregulated in ovarian tumor tissues and cells, and MIR503HG overexpression impaired the proliferative, invasive and EMT properties, and facilitated cell apoptosis in ovarian cancer cells." (PMID 35771155, 2022). "MIR503HG inhibited SPI1-mediated transcriptional activation of TMEFF1 by binding to SPI1, and suppressed the expression of TMEFF1, thus hindering the progression of ovarian cancer." (PMID 35771155, 2022).
triple-negative breast carcinoma (1 paper, 2019). An invasive breast carcinoma which is negative for expression of estrogen receptor (ER), progesterone receptor (PR), and human epidermal growth factor receptor 2 (HER2). "In conclusion, MIR503HG functions as a tumour suppressive long non‐coding RNA in triple negative breast cancer." (PMID 31062436, 2019).
tumor (8 papers, 2018 to 2024). "We proposed that the downregulation of MIR503HG in tumor tissues was caused by DNA hypermethylation, a mainly epigenetic mechanism for eukaryotic genomes." (PMID 37416763, 2023). "This implies, that MIR503HG has cancer type-specific effects and can function as tumor suppressor or oncogene." (PMID 39676172, 2024). "For the first time, our study revealed that overexpression of MIR503HG substantially reversed the metastasis-promoting effect of NETs on NSCLC, which further suggested that MIR503HG plays a tumour suppressor role in cancers." (PMID 35707534, 2022). "Depletion of MIR503HG suppressed tumor cell proliferation in vivo and in vitro; conversely, its overexpression enhanced tumor cell growth." (PMID 29758012, 2018). "Important promoters of tumour angiogenesis can serve as therapeutic targets, including MALAT1, TUG1, LNC00323-003, PVT1, and MIR503HG." (PMID 35052495, 2022).
cancer (7 papers, 2019 to 2025). A tumor composed of atypical neoplastic, often pleomorphic cells that invade other tissues. "The human homolog of B130024G19Rik, NR2F2-AS1, has been studied in various cancers, as has C430049B03Rik and its human homolog MIR503HG." (PMID 39846680, 2025). "The GO enrichment analysis of TCGA datasets further demonstrates that MIR503HG expression positively correlates with genes involved in pro-tumorigenic pathways suggesting that MIR503HG promotes cancer cell survival." (PMID 39676172, 2024). "Among the SAL-downregulated lncRNAs, we identified MIR503HG, a lncRNA aberrantly expressed in different cancer types." (PMID 39676172, 2024). "Recently, lncRNA MIR503HG has been suggested to be dysregulated and involved in a variety of human cancers." (PMID 33932142, 2021). "Interestingly, our bioinformatic correlation analysis provides evidence that MIR503HG, in addition to its role in promoting cancer cell proliferation, also regulates various DNA repair factors." (PMID 39676172, 2024). "The function of MIR503HG in cancer regulation was also investigated." (PMID 38563016, 2024). "Interestingly, MIR503HG shows aberrant expression in different cancer types." (PMID 39676172, 2024). "The results showed that overexpression of MIR503HG decreased cellular senescence level, particularly in SAL-treated cells, confirming that MIR503HG inhibits cellular senescence in cancer." (PMID 39676172, 2024).
MIR503HG also shares sentences with these, for which no sentence is quoted: non-small cell lung carcinoma (1 paper); ovarian tumor (1); papillary renal cell carcinoma (1); prostate adenocarcinoma (1).